BRCA1 (BRCA1 DNA repair associated)
Diseases named in the same sentence as BRCA1 in open-access papers (continued):
Sharing a sentence is not in itself a finding about the gene and the disease.
breast cancer (continued). "Compared with White women, Nigerian women with breast cancer have different epidemiological and genetic risk factor profiles, such as younger age at diagnosis, later age at menarche, higher parity, and a relatively high germline mutation rate in BRCA1 and BRCA2 genes." (PMID 34836952, 2021). "However, HRT use is contraindicated for BRCA1/2 mutation carriers with a history of breast cancer." (PMID 33480862, 2021). "Besides, a metanalysis by Barretta and colleagues, including 105,220 breast cancer patients from 60 studies, showed worse OS and worse breast cancer specific survival (BCSS) in BRCA1 mutation carriers while BRCA2 carriers had worse BCSS only in comparison to sporadic cases." (PMID 34206661, 2021). "In relation to hereditary breast cancer, RXR has been described to be overexpressed in BRCA1-mutated BC cells." (PMID 34359656, 2021). "The results of this study point to innate systemic metabolic differences in gBRCA1+ women independent of cancer incidence and raise the question as to whether or not constitutional alterations in energy metabolism may be involved in the etiology of BRCA1-associated breast cancer." (PMID 33898308, 2021). "Therefore, patients with tumors carrying DNA mismatch repair (MMR) deficiency (MMRd), homologous recombination deficiency (HRD), breast cancer 1/2 (BRCA1/2) genetic defects, or other defects in DDR genes, who present more TMB and neoantigens, can benefit from DDRi." (PMID 34930377, 2021). "Defects in the expression of DNA damage repair (DDR) genes such as BRCA1/2, homologous recombination is compromised forcing cells to adopt alternative error-prone repair pathways, which are associated with high risk and a significant cause of the progression of breast cancer." (PMID 34625530, 2021). "Observational studies have shown that BRCA1 mutation carriers giving birth at aged 30 years or older might have a lower risk of breast cancer, with a higher risk of breast cancer of a BRCA2 mutation carrier's first pregnancy happening before the age of 30 serving as a contrast." (PMID 34376160, 2021). "To explore whether small-molecule inhibitors can sensitize cancer cells to PARPi, we performed a drug combination screen in BRCA1-deficient breast cancer cell line of HCC1937 and BRCA2-deficient CRC cell line of HCT-15, which express mutant-type BRCA1 or BRCA2 protein but modestly respond to PARPi." (PMID 33589588, 2021). "Notably, Pdgfrβ and Ck14 doubly positive tumor cells were also detected in lung metastases of p18−/−;Brca1MGKO and p16−/−;Brca1MGKO mammary tumors, which demonstrated that the metastases were derived from Brca1-deficient basal-like mammary tumors with an increased Pdgfrβ expression." (PMID 33478572, 2021). "In this study, we investigated whether the 313 variant–based PRS for breast cancer is associated with contralateral breast cancer risk among women of European ancestry with pathogenic variants in BRCA1/2 and explored the implications for contralateral breast cancer risk prediction for these women." (PMID 34113011, 2021). "TNBC represents approximately 15–20 percent of breast cancers (BC) diagnosed worldwide and occurs more often in younger, black women and patients harboring mutations in breast related cancer antigens 1 and 2 (BRCA1/2)." (PMID 32235297, 2020). "Another interesting observation from this work was the upregulation of MSP and RON expression in breast cancer 1 (BRCA1)‐deficient mammary tumors compared to BRCA1 WT tumors, which suggests that MSP–RON signaling may be evolutionarily selected in highly genomically unstable tumors." (PMID 32484599, 2020).
breast cancer (continued). "Since BRCA1 c.3257del is classified as a frameshift variant that theoretically leads to the termination codon and most frequently leads to ER/PR-negative status in breast cancer, we turned our investigation to the alterations of BRCA1 mRNA and protein expressions in breast cancer cell lines." (PMID 32879886, 2020). "In addition, ongoing trials should determine whether PARP inhibitors might improve outcome when administered in the adjuvant or neoadjuvant setting in early luminal breast cancer patients with BRCA1/2 mutation." (PMID 33302444, 2020). "It is controversial whether BRCA1/2 mutations in breast cancer are associated with poor prognosis." (PMID 32322271, 2020). "The sample size of our analyzed series (n = 33) and the number of detected BRCA1/2 mutations (n = 5) were small, thus we could not provide conclusive data about the prevalence and spectrum of BRCA1/2 mutations in young breast cancer patients from North of Morocco." (PMID 32894085, 2020). "Given that our scRNA-seq study was conducted on the Brca1-deficiency mouse breast cancer model to elucidate the microenvironmental impact of obesity on breast cancer development, our findings may form the basis for the future development of obesity-related therapeutic and preventive interventions." (PMID 32785175, 2020). "Furthermore, these miRNAs could have potential value as a complementary clinical diagnostic tool to identify breast cancer patients that could benefit from BRCA1/2-mutations genetic testing and personalized clinical management." (PMID 32087690, 2020). "Among inherited mutations, BRCA1 e BRCA2 (BReast CAncer) suppressor genes are the most involved in BC susceptibility." (PMID 32722276, 2020). "Therefore, developing novel radiosensitivity assays could be a promising approach for pre-screening the BRCA1/2 mutation carriers and predict the overall increased risk mainly in the relatives of breast cancer patients." (PMID 33013205, 2020). "Therefore, we hypothesized that the recurrent or case-only BRCA1/2 variants from familial breast cancer patients might be considered as susceptibility loci for high-risk population screening." (PMID 32879886, 2020). "As the risk of bilateral breast cancer is relatively higher in younger patients, mode of detection other than breast ultrasonography and mammography such as MRI might be required for high risk patients younger than 35 years or with known BRCA1/2 mutations." (PMID 33204419, 2020). "In summary: DeltaNp73 may play a role in breast cancer susceptibility of BRCA1 mutation carriers." (PMID 32825620, 2020). "However, the majority of hereditary breast and ovarian cancers (HBOC) are due to highly penetrant germline BRCA variants, which are inherited in an autosomal-dominant fashion: breast cancer susceptibility gene 1 (BRCA1) or breast cancer susceptibility gene 2 (BRCA2)." (PMID 32806537, 2020). "Thus, the current study aimed toscreen the Punjabi population from Amritsar and adjoining regions of Punjab, NorthIndia, for the four variants of BRCA1 [c.190T>C (p.Cys64Arg),1307delT, g.5331G>A (p.G1738R) and c.2612C>T (p.Pro871Leu)] to investigatetheir association with breast cancer risk." (PMID 32453341, 2020). "In addition, consistent with the previous studies that linked the genes underlying the HRD to Signature 3 in breast cancer, the subnetworks identified for Signature 3 C/D contain BRCA1 and BRCA2 genes, two important genes in HR-mediated double-strand break (DSB) repair." (PMID 32471470, 2020). "Similarly, when administered before anthracycline-cyclophosphamide, the neoadjuvant olaparib-paclitaxel combination was not superior to carboplatin–paclitaxel, in patients with HER2-negative breast cancer and BRCA1/2 mutation, or homologous recombination defect." (PMID 32471249, 2020).
breast cancer (continued). "However, the prevalence of BRCA1/2 mutations is still unknown among Moroccan young breast cancer patients and it is still unclear whether these genetic factors may explain the higher rate of EOBC in Morocco." (PMID 32894085, 2020). "Breast cancer (BC) in patients with germline mutations of BRCA1/BRCA2 are associated with benefit from drugs targeting DNA damage response (DDR), but they account for only 5–7% of overall breast cancer." (PMID 32719318, 2020). "Moreover, sporadic breast cancer cases, which harbor BRCA1 deficiency, may benefit from this IHC since they become more and more important in clinical practice, with respect to anti-PARP based therapy." (PMID 32290274, 2020). "For example, women whose ovarian or breast cancer is associated with pathogenic variants in BRCA1/2 may be treated with poly (ADP-ribose) polymerase (PARP) inhibitors that have been approved for the management of advanced BRCA1/2 mutation-associated ovarian cancer." (PMID 32090079, 2020). "Interestingly, other genes known to have a strong tissue‐specific disease presentation, such as BRCA1 (72% of women who inherit a harmful BRCA1 mutation develop breast cancer by the age of 8060) also lack significant cis‐acting eQTLs in GTEx within the relevant (ie, breast) tissue." (PMID 32557794, 2020). "However, whether other driver mutations also contribute to the breast cancer initiation and progression associated with BRCA1 deficiency is not well understood." (PMID 32978388, 2020). "BAP1, originally identified as an associated protein of the breast cancer susceptibility gene product BRCA1, is a nuclear deubiquitinase with ubiquitin carboxy-terminal hydrolase activity and contributes to the inhibition of E3 ligase function of BRCA1/BRAD during DNA damage response." (PMID 33072611, 2020). "Breast cancer incidence peaks or plateaus at a younger age (early 40s) in BRCA1 than BRCA2 mutation carriers, perhaps suggesting that much of the carcinogenic process in BRCA1 mutation carriers takes place before women typically have RRSO and could influence disease incidence." (PMID 31948486, 2020). "Therefore, VDR may induce factors that transactivate the BRCA1 gene and its expression mediates the antiproliferative effect of 1,25(OH)2D, but this pathway may be disrupted in breast cancer by pathogenically mutated BRCA1 or/and aberrant VDR signaling." (PMID 32456160, 2020). "However, metformin (5 mM) treatment suppressed the BRCA1 haploinsufficiency-driven overexpression of RANK-L and synergistically reduced the self-renewal capacity in BRCA1-mutated basal-like breast cancer cells, resulting in a decrease in the breast cancer-initiating cell population." (PMID 32883003, 2020). "While BRCA1 mutations are rare in sporadic breast cancers, BRCA1 dysfunction has also been reported in 24–63% of these cases and is associated with reduced or complete loss of BRCA1 mRNA and protein abundance, BRCA1 protein mis-localisation, as well as BRCA1 gene promoter methylation." (PMID 33212987, 2020). "This is the first study to our knowledge to systematically evaluate whether tailored recommendations related to dietary habits, weight management and PA may be effective in reducing ovarian and breast cancer risk among women with BRCA1/2 pathogenic germline gene variants." (PMID 32165993, 2020). "PARP1 was proposed as a new treatment for cancer, as the synthetic lethality concept suggested that its depletion in breast-cancer patients with germline mutations in the BRCA1 or BRCA2 genes, key molecules in the homologous recombination (HR) pathway, could cause cancer cell death." (PMID 32046300, 2020).
breast cancer (continued). "Historically, BRCA1/2 pathogenic variants are suspected in families with multiple women with BC and/or OVC, early ages of cancer onset, bilateral or male breast cancer." (PMID 33643918, 2020). "Although a recent study has indicated that multiple Fanconi anemia pathway genes including BRCA1 are required for mitophagy,[qv: 39] its underlying mechanism remains poorly defined, and the relationship of defective mitophagy with BRCA1‐associated breast cancer development is unknown." (PMID 32195105, 2020). "Triple-negative breast cancer (TNBC), which represents an aggressive BC subtype with poor prognosis, is highly associated with mutations of tumorsupressor BRCA1." (PMID 31817446, 2019). "Furthermore, using data from 651 breast cancer patients in Southern China, one BRCA1 pathogenic variant (c.981_982delAT) and three BRCA2 pathogenic variants (c.3109C>T, c.7436_7805del370, and c.9097_9098insA) were analyzed and reported as Chinese founder mutations." (PMID 31143373, 2019). "Interestingly, 16–25% of breast cancers are caused by mutations in the BRCA1 and BRCA2 genes." (PMID 31597313, 2019). "The presence of bilateral breast cancer (BBC), number of BC cases and the presence of ovarian cancer (OC) increased (respectively) 5.797, 5.033 and 4.412 times the risk of being a BRCA1/BRCA2 mutation carrier." (PMID 31244284, 2019). "Therefore, we indicate the need for further studies to explain the role of redox balance disturbances in the pathogenesis of breast cancer, because the abnormalities in redox balance observed in our patients are caused not only by cancer but also by the BRCA1 mutation." (PMID 31597313, 2019). "Bearing in mind that the population incidence of breast cancer is about 10 times the incidence of ovarian cancer, these findings indicated that the risks for breast and ovarian cancers were similar in carriers of the Norwegian founder path_BRCA1 variants, but with later onset of ovarian cancer." (PMID 30678073, 2019). "In addition, the UGM can be used to screen many breast cancer-associated genes, such as BRCA1, BRCA2, PTEN, BRIP1, etc., provides better accuracy, robustness and efficiency, the method of identification differentially expressed genes in high-throughput sequencing." (PMID 31865918, 2019). "However, at the moment it is impossible to determine whether the BRCA1 mutation in patients with breast cancer is the cause or effect of the oxidative stress." (PMID 31597313, 2019). "This may be due to the fact that testing for BRCA2/BRCA1 mutations is perceived as more informative for prevention than determining treatment options in breast cancer, although recent research on the BRCA1/BRCA2 mutation carriers’ response to carboplatin therapy suggest this perception may change." (PMID 30689103, 2019). "Given the established role of female sex hormones in the pathogenesis of BRCA1 mutation-driven breast cancer, different studies investigated whether RANKL/RANK axis could act as a downstream mediator of sex hormones in breast tumorigenesis of BRCA1 mutation carriers." (PMID 30621730, 2019). "Thus, the goal of this study was to prospectively evaluate whether plasma RANKL levels are associated with the risk of breast cancer among women with a BRCA1 or BRCA2 mutation." (PMID 31069010, 2019). "The carrier of BRCA1 variant c.4850C>A was diagnosed with right breast cancer at age 33 and had a positive family history of breast cancer (a mother diagnosed with breast cancer at age 57, a daughter and maternal aunt diagnosed with breast cancer before age 40)." (PMID 31131559, 2019). "Furthermore, PTEN loss was reported to be enriched in BRCA1-mutated breast cancers." (PMID 31022191, 2019). "Loss-of-function mutations of the breast cancer type 1 susceptibility protein (BRCA1) are associated with breast (BC) and ovarian cancer (OC)." (PMID 31840082, 2019).
breast cancer (continued). "The increased sensitivity of TN breast cancer cells to olaparid in presence of NAMPT inhibitor could be due most probably to the defect in homologous recombination genes (such as loss-of-function BRCA1 or BRCA2 mutations)." (PMID 31803365, 2019). "A recent research found that breast cancer type 1 susceptibility protein (BRCA1) was related with the suppression of FOXA1 expression in BC cell lines and that BRCA1 mutation was linked to FOXA1 promoter methylation and silencing in BCs." (PMID 31540486, 2019). "First, as a result of the rarity of PALB2-associated breast cancers, the small sample size may have limited the detection of significant differences in the exploratory analyses comparing PALB2-associated breast cancers with non-BRCA1/2/PALB2-associated breast cancers from TCGA." (PMID 31428676, 2019). "Interestingly, the proportion of PALB2-associated breast cancers displaying mono-allelic PALB2 inactivation was comparable to the one of BRCA1-associated and BRCA2-associated breast cancers from TCGA harboring BRCA1 or BRCA2 mono-allelic inactivation, respectively." (PMID 31428676, 2019). "Therefore, the aim of the present investigation was to compare BRCA1 expression in the setting of triple-negative and luminal tumors and to study the association of BRCA1 expression with clinicopathological features in Iranian breast cancer patients." (PMID 28646826, 2018). "Moreover it is suggested that BRCA analysis should also be meant for determination of treatment strategies and breast cancer Pakistani patients diagnosed with age less than forty should be screened for BRCA1-185 Del AG as a part of routine diagnostic marker before treatment." (PMID 30344568, 2018). "Moreover, higher expression of BRCA1 was associated with significant shorter OS in ER-positive breast cancer patients from Curtis breast published on oncomine platform and the meta-analysis of breast cancer patients from 27 data sets in GEO database." (PMID 29686231, 2018). "Thus, proton radiation could be particularly effective in treating breast cancers with genetic deficiencies for HR genes, including BRCA1." (PMID 31773035, 2018). "Ovarian cancer showed the strongest association with breast cancer (joint P < 10−11) and it may be attributable to BRCA1/2 mutations as in the histological analysis breast cancer was associated with serous ovarian carcinomas, which have been reported to be related to BRCA1/2 mutations." (PMID 30069056, 2018). "Additionally, increased FA biogenesis may be associated with breast cancer in women with inherited germ line breast cancer 1, early onset (BRCA1) mutations." (PMID 29342092, 2018). "Furthermore, BRCA1 deficiency in breast epithelial cells could disable HR mechanisms for DNA damage, resulting in genomic instability and increased breast cancer risk." (PMID 29497033, 2018). "Along with activation of the Akt pathway, estrogen promoted EMT and proliferation in Brca1-deficient mammary tumor cells, which prompted us to test whether pharmaceutical inhibition of Akt activity has any effect on Brca1-deficient cell proliferation and tumor progression." (PMID 29996906, 2018). "In addition, transcriptional signatures have been generated that distinguish BRCA1/2-associated and sporadic ovarian or breast cancer and may be able to recognize tumors with HR deficiency, BRCAness phenotype and/or PARP sensitivity." (PMID 30544963, 2018). "For the woman with an inherited BRCA1 or BRCA2 mutation who wishes to do everything possible to avoid developing breast cancer, risk-reducing mastectomy at age 25 is undoubtedly the optimal strategy; however, for many mutation carriers, other factors may be of equal or greater importance." (PMID 30513626, 2018).